IL21 (interleukin 21)
Diseases named in the same sentence as IL21 in open-access papers (continued):
Sharing a sentence is not in itself a finding about the gene and the disease.
tumor (continued). "The expressed IL-21 not only regulated the levels of IFN-γ and TNF-α in the mouse serum but also increased the expression of NKG2D and MIC A molecules in the tumor tissues." (PMID 24444073, 2014). "After 6 days, the tumor volume had gradually decreased in the IRES/combination group, and was marginally suppressed in the IRES/GM-SCF-IL-21, IRES/GM-SCF, and IRES/IL-21 groups, but had increased rapidly in both the IRES/GFP and control groups." (PMID 24350772, 2013). "The tumor weight averaged 0.207, 0.522, 0.873, 0.843, 1.439, and 1.591 g for IRES/combination, IRES/GM-SCF-IL-21, IRES/GM-SCF, IRES/IL-21, IRES/GFP, and the control group, respectively, which were significantly different (P < 0.01)." (PMID 24350772, 2013). "Cytokines such as interleukin (IL)-6, IL-17A, IL-21 and tumor necrosis factor (TNF)-α contribute to the formation of a tumor-supportive microenvironment, while interferon (IFN)-γ is supposed to exert tumor-suppressive functions." (PMID 23109839, 2012). "Hypomethylated genes in the TNF network were cytokines (CCL3, CCL4, CCL7, CCL8, CCL22, IL21, IL17A, EBI3) that can either stimulate or inhibit tumor growth and progression." (PMID 22768131, 2012). "We then detected cytokines IL-1β, IL-6, IL-17A, IL-21, IL-23 or TGF-β by ELISA in sera and supernatants from both normal and tumor tissues cultured ex vivo." (PMID 22994684, 2012). "The presence of the Th17-related cytokine transcripts, IL-17A (IL-17), IL-21 and IL-22 mRNA, and of GFP was analyzed in extracts from the eyes 19 days after inoculation of tumor cells or injection of PBS." (PMID 21949734, 2011). "From a functional standpoint, IL-21/IL-15-treated cells secreted copious amounts of IFN-γ, GM-CSF and CCL3/MIP-1α, and expressed cell surface CD107a upon contact with NK-sensitive tumour targets, a measure of exocytosis of NK secretory granules." (PMID 19712464, 2009). "Finally, the NK cells differentiated with IL-15 and IL-21 underwent exocytosis of secretory granules, as measured by a flow cytometry-based CD107a degranulation assay, upon co-culturing for 4 hours with NK-sensitive tumour cell targets, indicating the acquisition of cytolytic potential." (PMID 19712464, 2009). "Several studies have shown that genetically engineered IL-21-secreting murine tumors activate potent NK and CD8+ T cell mediated anti-tumor responses." (PMID 16772043, 2006). "Furthermore, IL-21 co-expression improved the in vivo persistence of CAR-NK cells and significantly suppressed tumor growth in a xenograft Raji lymphoma murine model, leading to prolonged survival of CD19+ tumor-bearing mice." (PMID 40176196, 2025). "However, tumor tissue from the patients who underwent GTR secreted higher levels of FGF-2 (P < 0.001), as well as ENA-78, MCP-3, and IL-21 (all, P < 0.05)." (PMID 39923035, 2025). "For example, the co-expression of IL-15 and IL-21 enhances survival, proliferation, and functionality, while engineering these cells to express chemokine receptors such as CXCR3 and CCR5 improves their tumour-homing ability." (PMID 40624498, 2025). "In renal cancer xenograft models, these IL-21-armed cells achieved durable, recurrence-free tumor control without evidence of cytokine-related toxicity." (PMID 40718496, 2025). "The analysis shows that the concentrations of IL-21 and IL-22 do not differ significantly depending on the malignancy grade of the tumour." (PMID 40729006, 2025). "In such cases, the development of IL-21-secreting CAR-NK cells may provide enhanced mechanistic synergy and overcome tumor resistance mechanism." (PMID 40176196, 2025). "IL-10 and IL-21, but not IL-6, activate STAT3, promote tumor-specific Texterm cell-associated gene expression, and suppress TexProg cell-related gene expression, resulting in the development and enhanced effector functions of Texint cells in tumors." (PMID 38582965, 2024).
tumor (continued). "The combination of GM-CSF and IL-21 may activate both innate and adaptive immunity, potentially reversing the immunosuppressive TME and enhancing anti-tumor immunity." (PMID 39830516, 2024). "Furthermore, cytokines such as IL-6, IL-21, IL-17A, and tumor necrosis factor-α (TNF-α) induce tumor-supportive microenvironment, while interferon-γ (IFN-γ) exerts tumor-suppressive response." (PMID 38741166, 2024). "CD4(+) T cells expressing IL-17 and IL-21 constituted less than 0.89 ± 0.11% of all cytokine-producing CD4(+) T cells, indicating minimal involvement of Th17 and T- follicular helper (Tfh) in the tumor microenvironment." (PMID 38895115, 2024). "Meanwhile, Analysis of RNA-seq data from the Cancer Genome Atlas showed that IL-21 transcript was barely detectable in numerous tumors including HCC, predicting an absence of IL-21 in the tumor microenvironment." (PMID 38643203, 2024). "Combining a vaccinia virus expressing IL-21 treatment with anti-PD1 and a PI3Kδ (phosphoinositide 3-kinase-δ) inhibitor to prevent virus uptake by macrophages was able to significantly inhibit tumor growth and increased overall survival in an established pancreatic tumor model." (PMID 38638431, 2024). "In our study, we found that the IL-21-supplemented TCR-T showed a signature of naive-like T cells after activation and simultaneously retained its effector function against tumor cells, reflecting the unique biological effects of IL-21 in supporting T cell antitumor immunity." (PMID 38643203, 2024). "Moreover, we determined the potential anti-tumor effects of the triple combination involving MWA, IL-21, and anti-PD-1 mAbs." (PMID 38833177, 2024). "The combination of MWA with IL-21 exhibited a robust abscopal anti-tumor effect, enhancing the effector function of CD8+ T cells and facilitating dendritic cells' maturation and antigen presentation in the untreated tumor." (PMID 38833177, 2024). "Similarly, the administration of human UC-MSCs secreting IL-21 into SKOV3 nude mice with ovarian tumours reduced tumour burden in the transplanted mice, as seen by the decreased tumour size." (PMID 39416732, 2024). "Th17 cells are a rare subset of T helper cells whose role in the tumor microenvironment is context-dependent and not yet well understood, though they have been observed to secrete IL-21." (PMID 38750495, 2024). "Moreover, the NicheNetR analysis revealed the potential ligands expressed by C3–4 of LN tumor cells that drive exhausted signatures of CD8 TDYS in RR TFHL, including IL21, TNF, TGFB1, CD80, and CD86." (PMID 38012392, 2024). "Therefore, IL-21 released from CRA-activated T cells allows B cell differentiation and produces high titers and affinity of antitumor autoantibodies to inhibit tumor growth." (PMID 37081540, 2023). "GPC3 CAR-T cells expressing IL-15 and IL-21 exhibited significantly greater anti-tumor efficacy in mice compared to CAR-T cells without IL-21 expression." (PMID 38090585, 2023). "Despite the partial knowledge of IL-21’s abilities in tumor microenvironment, the use of IL-21 as a real medicine is currently not applied." (PMID 37759505, 2023). "Three-dimensional tumor models consisting of 624-MEL cells were co-cultured with human peripheral blood lymphoid cells (PBLs) in presence of the cytokines IL-2, IL-7, IL-15, IL-21 and IFN-γ." (PMID 37923822, 2023). "Moreover, Tfh cells produce IL-21, which increases antitumor immunity by promoting the expression of IFN-γ and granzyme B in tumor-infiltrating CD8+ T cells." (PMID 36776832, 2023). "Therefore, IL21 and anti-PD-1 result in the reorganization of cellular networks in the TME that favors tumor elimination." (PMID 37546701, 2023). "It has been reported that tumor-specific B cell drive activation of tumor-specific Tfhs and activated Tfhs could enhance the effector function of CD8+ T cells by secreting IL21." (PMID 36869384, 2023).
tumor (continued). "While NK cell expansion using K562-mb-IL-21 feeder cells and IL-15 stimulation can enhance NK cell metabolic fitness allowing them to thrive in the TME, efficient homing of adoptively transferred NK cells to the tumor remains to be addressed." (PMID 38022679, 2023). "Collectively, these data demonstrate that IL21-anti-HSA and anti-PD-1 mAb synergistically enhance a tumor site–focused CD4+ T cell–mediated antitumor immune response through promoting the hyperactivated/exhausted CD4+ T-cell subtype and CD4+ T-cell clonal expansion." (PMID 37546701, 2023). "Prior to conducting the assay, we identified a subset panel of factors known to mediate the induction of apoptosis in tumor cells: IL-27, IL-1b, IL-2, CXCL10, IL-12p70, G-CSF, IFN-g, TNF-a, IFN-a, CCL2, IL-9, TNF-b, TRAIL, IL-18, IL-21, TSLP." (PMID 37468934, 2023). "In vitro studies employing primary cells from EBV positive DLBCL tumor cells and cell lines revealed EBV prevented IL-21-induced apoptosis, and EBV infection of B cells provided survival factors to EBV+-DLBCL cell lines and modulated cytokine-induced specific chemotaxis in these cells." (PMID 36765813, 2023). "Combination of ICI with recombinant IL‐21 (rIL‐21) is a strategy for enhancing the tumor suppressor effect of ICI therapy in tumors with low/no expression of MHC‐I." (PMID 35301813, 2022). "IL-21-dependent stimulation of functional intra-tumoral CD8+ cells was able to overcome the checkpoint blockade resistance in renal cancer and enhanced the antitumor activity of tumor-infiltrating lymphocytes." (PMID 35884974, 2022). "Furthermore, induced secretion of IL-21 by CD19-CAR-T cells can even maintain CAR-T cells in early memory phenotype and enhance anti-tumor activity in vivo, which was already demonstrated in mice transplanted with Ramos B cells." (PMID 36248810, 2022). "However, NK cell activity can be altered by numerous components of the tumor microenvironment, including immunosuppressive cytokines, such as TGF-β, and pro-inflammatory cytokines, such as IL-12, IL-15, IL-18, and IL-21." (PMID 35203609, 2022). "IL-21-treated NK cells secreted high levels of IFN-γ, which enhanced NK cell activation through extracellular signal-regulated kinase and signal transducer and activator of transcription (STAT) 1 signaling pathway, thus inhibiting tumor growth." (PMID 36601109, 2022). "In the intestinal tract, tumor-associated bone marrow cells secrete IL-23, which affects the polarization of Th17 cells, followed by the production of IL-17A, IL-21, TNF-α, and IL-6, which induce a tumor-promoting inflammatory response and promote CC development." (PMID 36147322, 2022). "Clinical trials using IL-21 in combination with cetuximab confirm preclinical findings, reporting increased cytokine secretion, enhanced ADCC and achieving stable disease in patients with different tumor types." (PMID 34557197, 2021). "Given that IL-21 plays a positive role in PD-L1-induced Treg generation, we next investigated the relationships between the expression patterns of IL-21, PD-L1, and FOXP3 in tumor specimens." (PMID 34026621, 2021). "In order to minimize systemic toxicity and induce the accumulation of high cytokine concentrations at the tumour site, CAR‐T cells were modified to produce IL‐12, IL‐18, IL‐7, IL‐15 and IL‐21 cytokines, and activation and persistence of CAR‐T cells were, therefore, enhanced in vivo." (PMID 34585512, 2021). "PD-1Ab21 treatment show potent antitumor effects in established tumor-bearing mice accompanied with an increased frequency of TSCM and robust expansion of tumor-specific CD8+ T cells with a memory phenotype, and is superior to a combination of PD-1 blockade and IL-21 infusion." (PMID 33574265, 2021). "Recently two independent reports showed that targeting IL-21 directly to T cells rather than systemic delivery in combination with PD-1 therapy improved tumor immunity." (PMID 33815400, 2021).
tumor (continued). "Among them, IL-2, IL-7, IL-15 and IL-21 have been widely utilized for the CAR-T cell preparation, because these cytokines play pivotal roles in fueling T cells to thrive, combat tumors and drive long-lived memory against tumor metastasis or relapse." (PMID 34179083, 2021). "In a direct comparison, using CAR NK cells generated from the same CB donor, mice receiving CAR-NK cells expanded with uAPC achieved better tumor control and survived significantly longer when compared to animals treated with CAR-NK cells generated with C9/IL-21." (PMID 33717142, 2021). "Tumor-infiltrating T, B, and NK cell levels and plasma concentrations of Th1 (IL-2, IFN-γ, and TNF-α), Th2 (IL-4, IL-5, IL-6, and IL-10), Th9 (IL-9), and Th17 (IL-17A, IL-17F, IL-21, and IL-22) cytokines were evaluated." (PMID 32802733, 2020). "Moreover, the function of IL-21 on CRC progression is controversial, with both tumour-promoting and antitumour effect have been reported 47, 48, 59-61." (PMID 32760201, 2020). "Testing combinations of various cytokines in T cell culture media revealed that tumor antigen specific CD4+ T cell growth was improved by culturing in IL-1β, IL-2, IL-6, IL-7, IL-15, IL-21, IL-23, and TGFβ, and that the addition of TGFβ was critical for the improved performance of the cocktail." (PMID 33362774, 2020). "IL-21 is known to stimulate NK and CD8 + T cell anti-tumor response." (PMID 33298174, 2020). "Upon in vitro expansion with IL-21, human Vγ9Vδ2 cells display increased levels of granzyme B and increased production of IFN-γ after activation, resulting in enhanced cytotoxic activity toward tumor cells." (PMID 33042132, 2020). "Also, adoptive transfer of IL-21-producing CD4+ T cells into tumor-bearing mice induced generation of a CX3CR1+ effector CD8+ T cell pool, leading to improved tumor control." (PMID 33123174, 2020). "Furthermore, in NOD/SCID mouse xenograft model experiments, we found that IL-21 treatment increases glucose uptake and angiogenesis in EBV-positive DLBCL tumours." (PMID 32704112, 2020). "Of note, the numbers of IL21 or IL26 positive T cells were not significantly correlated to tumor size, histological grading, or lymph node positivity (p ≥ 0.2510)." (PMID 31948053, 2020). "Under our experimental conditions, we did not see effects of IL-21 on tumor growth or vascularization." (PMID 31540511, 2019). "Here, tumor cells were engrafted on the chorioallantoic membrane (CAM) of fertilized chicken eggs in the presence or absence of IL-21 at day 9 of chick development." (PMID 31540511, 2019). "Given the fact that IL-21-mediated Blimp-1 regulation is not restricted to tumor cells and is rather a mechanism found in immune cells, this is an example of how tumor cells can hijack immune-related pathways." (PMID 31540511, 2019). "Studies have proved that CD4+ T cells exert antitumor activities by activating and recruiting macrophages and eosinophils, which produce tumor-destroying free radicals and induce the secondary expansion and accumulation of CD8+ T cells by co-expressing IL-21 and IFN-γ38,39." (PMID 30120362, 2018). "IL-21, a member of the γc family, has also been reported to improve CD8+ T-cell function through regulation of IFN-γ, granzyme B and perforin production, and survival in infection and tumour models." (PMID 28798332, 2017). "Although Vγ2Vδ2 T cells grown in IL-15 did not mediate better anti-tumor immunity, synergistic effects between IL-15 and a second γC cytokine, IL-21, have been reported." (PMID 28239463, 2017). "Astonishingly, none of the recipient mice who underwent IL-21 treatment developed graft-versus-host disease (GVHD) in the MHC-matched allogeneic setting while the graft-versus-tumor (GVT) effect was strongly retained." (PMID 28615039, 2017). "Finally, it has been suggested that both IL-15 and IL-21 are able to enhance the in vivo anti-tumor effects of CD8+ T cells and, in some cases, potentiate tumor regression." (PMID 28146052, 2017).
tumor (continued). "Plasma levels of the NK cell-activating cytokines IL-2, IL-15, IL-18, and IL-21 increased substantially within the first 2 days after CY+TBI compared to their plasma levels in 4T1 tumor-bearing mice not subjected to chemo-irradiation." (PMID 27915436, 2017). "Our data also suggest the essential role of IL-21R signalling in Grail−/− CD8+ T-cell function, since Grail−/− CD8+ T cells in the absence of IL-21 signalling expressed significantly low level of cytolytic cytokines and failed to suppress tumour growth." (PMID 28798332, 2017). "Interestingly, they also noted that DTA-1 enhanced IL-21 secretion from CD4 T cells in an IL-9-independent manner and proposed that DTA-1 enhances anti-tumor responses through TH9 cell-derived IL-9 and, possibly, IL-21." (PMID 27832300, 2017). "Therefore, IL-21 exposed CART cells showed the greatest persistence in animal models and the administration of this cytokine in vivo supported greater tumor eradication than other cytokines, excluding IL-15." (PMID 27409425, 2016). "Moreover, IL-21 together with IL-15 expands antigen-specific CD8+ T-cell numbers and their effector function, resulting in tumor regression." (PMID 26966515, 2016). "IL-21 was upregulated in the colon lesions of Apcmin/+ mice as compared with the non-tumor mucosa and lack of IL-21 in such mice resulted in a dramatic reduction of both tumor incidence and size." (PMID 25839161, 2015). "In this context, the combination of IL-21 and CpG-685 has potential not only to directly target CLL B cells but also to enhance the patient's immune response, recruiting other immune cells to target the tumor." (PMID 26158860, 2015). "In supernatants of HPV-positive tumors upon PMA and ionomycin stimulation we detected higher levels of IL-10, IL-17, IL-21, TNFα and IFNγ compared to supernatants of HPV-negative tumor samples; however, only the levels of IL-17 showed statistically significant differences (p = 0.030)." (PMID 25949860, 2015). "Other reports showed that IL-21 combined with IL-15 preserved memory type features and CD28 expression of human CD8+ tumor-infiltrating lymphocytes (TILs) or CTLs induced by antigen priming, allowing the generation of expanded CTL populations suitable for in vivo use." (PMID 25961061, 2015). "To understand the mechanisms of antitumor efficacy induced by hUCMSCs- LV-IL-21, we examined the serum cytokines of IL-21, IFN-γ, and TNF-α, which have an important functions in antitumor immunity and their levels indirectly represent the capacity of rejection of tumor in bearing-tumor nude mice." (PMID 24444073, 2014). "A number of therapeutic approaches have been proposed to enhance the anti-tumor effect of suicide gene therapy by inducing an immune response to tumor cells via co-expression of cytokine genes, such as IL-2, IL-2 and TNF-α, IL-12, and IL-21." (PMID 23441198, 2013). "Current studies on the treatment of tumors by GM-SCF or IL-21 mostly focus on enhancing CTL and NK cell-mediated activity or increasing genes that can be expressed by tumors and recognized by NK and CTL cells in tumor tissues." (PMID 24350772, 2013). "TIL were expanded from the tumor cell suspensions by stimulation with IL-2-, IL-15-, IL-21- or no cytokine-expressing aAPC, after which phenotype and function of the various cytokine-expanded TIL were analyzed." (PMID 23402380, 2013). "Mart-126L- and/or GP100154/209/280-specific CD8+ T cells could be detected to similar levels in fresh (i.e. unexpanded) and IL-2, IL-15 and IL-21 aAPC expanded TIL samples, indicating that tumor antigen specificity was maintained after aAPC-mediated expansion." (PMID 23402380, 2013). "The tumor was also significantly (P < 0.01) lighter in the IRES/GM-SCF-IL-21 group than was found in either the IRES/GM-SCF or IRES/IL-21 groups and was not significantly different (P > 0.05) between either the IRES/GM-SCF group or the IRES/IL-21 group." (PMID 24350772, 2013).